ANG (angiogenin)
Diseases named in the same sentence as ANG in open-access papers (continued):
Sharing a sentence is not in itself a finding about the gene and the disease.
cancer (continued). "Two enzymes, which have been tested to various extents for their specific cytotoxic activity in a range of cancer types, in cell culture and/or xenograft, are granzyme B (a serine protease) and angiogenin (human RNase A analogue)." (PMID 28536352, 2017). "Further modifications of angiogenin are currently undergoing cell model screening in fusion with αCSPG4 (scFv) for improved cytolytic efficacy against several cancers." (PMID 28657611, 2017). "In cancer research, angiogenin has been the topic of extensive scrutiny, since tumors produce blood vessel promoting growth factors, including angiogenin." (PMID 29231847, 2017). "Previous studies in human cancers revealed an unrecognized interplay between Angiogenin (ANG) and matrix metalloproteinase-2 (MMP2) leading to pronounced tumorigenesis." (PMID 27317771, 2016). "Although DNA abnormal methylation had been shown to result in anomalous silencing of several tumor suppressor genes in most types of cancer, this is the first report to show ANG ability to induce DNA abnormal methylation leading to bladder tumorigenesis." (PMID 27317771, 2016). "In contrast, the RNase angiogenin mediates vascularization to repair damaged blood vessels and during cancer development." (PMID 25019631, 2014). "RNH1 regulates the localization and activity of angiogenin which is involved in cell growth and survival mechanisms as well as in cancer establishment, growth and metastasis." (PMID 25058392, 2014). "Angiogenin (ANG) translocates to the nucleus of target cells, which is essential for angiogenesis and cancer cell proliferation." (PMID 23977052, 2013). "ANG undergoes nuclear translocation in its target cells, which is essential for angiogenesis and cancer cell proliferation." (PMID 23977052, 2013). "Angiogenin (ANG) acts on both vascular endothelial cells and cancer cells, but the underlying mechanism remains elusive." (PMID 22194915, 2011). "Finally, we showed that ANG promotes cancer cell proliferation and suggested that it was mediated by ANG-PLXNB2 and ANG-EGFR interactions." (PMID 38025776, 2023). "In addition to semaphorins, PlexinB2 was reported to act as receptor for the unrelated molecule angiogenin, controlling cancer cell survival and growth, beyond angiogenesis." (PMID 36722641, 2023). "However, a subset of tRNA halves are constitutively expressed in androgen receptor (AR)- or estrogen receptor (ER)-positive cancer cells even though they are processed by angiogenin." (PMID 37430089, 2023). "Indeed, it is known that ANG is involved in cancer progression by stimulating both tumour angiogenesis and cancer cell proliferation." (PMID 35955913, 2022). "Abnormal ANG levels are commonly seen in cancer, but this molecule has also been linked to other non-malignant diseases, including CVD." (PMID 34356982, 2021). "On the other hand, experiments carried out on cancer cells show that ANG may regulate intracellular copper levels." (PMID 34639045, 2021). "In primary cancer and recurrence, ANG and ANGST levels were similar." (PMID 33343662, 2020). "Angiogenin (ANG), also known as Ribonuclease 5, has various functions and associations with cancer and neurological diseases via its roles in angiogenesis and apoptosis suppression (Li, Yu & Hu, 2012; Steidinger, Standaert & Yacoubian, 2011; Tello-Montoliu, Patel & Lip, 2006)." (PMID 32509448, 2020). "The by-products formed by angiogenin cleavage regulate translation in human cancer." (PMID 32241281, 2020). "In cancer, the Tie2/ANG signaling pathway is clearly involved." (PMID 31659157, 2019). "Angiogenin (ANG) is a secreted ribonuclease (also known as RNase 5), identified in media from cancer cells, but also present in normal tissues, such as plasma and amniotic fluid, and secreted from vascular endothelial cells, aortic smooth muscle cells, fibroblasts." (PMID 31500197, 2019).
cancer (continued). "Our study revealed that serum ANG levels are elevated in cancer, especially CRC, AML, MM, and MDSs." (PMID 29736193, 2018). "Furthermore, Hu and colleagues demonstrated that hRNase5/ANG also enters the nucleus of cancer cells and induces ribosomal RNA transcription and the corresponding cell proliferation." (PMID 30449278, 2018). "Notably, a recent report indicated that plexin-B2 (PLXNB2) is the functional receptor of hRNase5/ANG in several cell types, including endothelial, cancer, neuronal, and normal and malignant stem/progenitor cells." (PMID 30449278, 2018). "Angiogenin levels are significantly higher in the serum of cancer patients than in healthy humans." (PMID 29261171, 2017). "Conceivably, cancer researchers would like to have a mouse knockout for the angiogenin gene." (PMID 29231847, 2017). "Indeed, our global DNA methylation microarray analysis showed that gene manipulation of ANG affected a variety of pathways, including cell migration, pathways in cancer, angiogenesis and tumor suppressor genes." (PMID 27317771, 2016). "ANG, a 14.2 kDa polypeptide member of the RNase A superfamily, which was originally isolated from conditioned media of HT-29 colon adenocarcinoma cells, is an understudied angiogenic factor in human cancers." (PMID 27317771, 2016). "Since angiogenin inhibitors block vascularization, it is a candidate anti-cancer drug." (PMID 25019631, 2014). "Here we provided evidence to support the hypothesis that ANG promotes cancer cell migration as well." (PMID 22194915, 2011). "Recently, ANG has been reported to directly enhance the proliferation of cancer cells such as HeLa cells and PC-3 cells, indicating that ANG plays dual roles in cancer progression by acting on both vascular and cancer cells." (PMID 22194915, 2011). "Finally, it has to be remembered that the capability to exert their activity in the nucleus is crucial for some RNases: indeed, ANG/RNase 5 needs to be enzymatically active but also to enter the nucleus to exert its fundamental angiogenic activity in both normal and cancer cells." (PMID 31849926, 2019). "This is noteworthy that abundances of C-reactive protein and angiogenin generally upregulated in cancers samples further increased in metastatic samples, while abundances of carbonic anhydrase 1 generally downregulated in cancer samples further decreased in metastatic samples." (PMID 26376850, 2015). "For instance, ALKBH3 can demethylate the m1A on tRNA, making tRNA more sensitive to angiogenin (ANG) cleavage, thereby generating tRNA‐derived small RNAs (tDRs) around the anticodon regions and promoting cancer cell proliferation, migration and invasion." (PMID 39175405, 2024). "Thus, angiogenin-induced tRNA halves may be an important target for cancer therapy." (PMID 37430089, 2023). "In tumoral samples, angiogenin signal mostly colocalized with CA9 staining, used here as a marker of cancer cells." (PMID 38025776, 2023). "In this work, we also showed that angiogenin and its two recently identified receptors, EGFR and PLXNB2,45,58 were upregulated at the protein level by ccRCC cancer cells as compared to their cell type of origin ex vivo." (PMID 38025776, 2023). "In endothelial cells, ROS-mediated angiogenesis via various stimuli via angiopoietin-I, angiogenin, VEGF, EGF, urotensin-II, shear stress, and hypoxia is a major contribution to cancer." (PMID 35421091, 2022). "Further, angiogenin and VEGF are probably the most widely found initiators of angiogenesis and ultimately plays role in the progression of cancer." (PMID 35421091, 2022).
cancer (continued). "The addition of benign cell lysate resulted in a significant increase of MMP9, VEGFA, ApoE, ANG, and MMP10, and the addition of cancer cell lysate resulted in a significant increase of MMP9, CA9, PAI1, ApoE, A1AT, ANG, and MMP10." (PMID 34204951, 2021). "While our results stress that hypoxia/ HIF1α/ANG axis has a great impact on mature tRNA-His-GTG cleavage, which suggested that the cancer cells produced more 5’tiRNA-His-GTG under the external stimulation of hypoxia." (PMID 33588913, 2021). "The dichotomous functions of ANG and PLXNB2 in HSPCs and MyePros prompted us to examine their function in prostate CSCs and in differentiated cancer cells, based on the rational that CSCs and HSPCs are regulated by similar mechanisms." (PMID 31942000, 2020). "The molecular characterization of angiogenic growth factors, such as VEGF-A, IL-8, PDGF-AA, Ang-1 and angiogenin, which are driven by HIF-2α, have been identified as key factors of cancer-related angiogenesis." (PMID 32708433, 2020). "In particular, a number of aptamers have been studied for their implications in specific recognition of cancer-related targets (e.g. thrombin, platelet-derived growth factor (PDGF), angiogenin, mucin, vascular endothelial growth factor (VEGF) and etc)." (PMID 30303958, 2018). "Serum ANG levels are currently not a clinical diagnostic marker for diseases; however, the significant changes in serum ANG levels that occur in cancers and CVDs indicate that it plays a role in the pathogenesis of these diseases and it may be a potential biomarker for these diseases." (PMID 29736193, 2018). "Different important target genes have been validated in different cancers, such as the transcriptional regulator PHF10, the pro-metastatic gene radixin, the pro-angiogenic gene angiogenin (ANG), the oncoprotein GAB1 and the pro-metastatic gene c-Met." (PMID 27057640, 2016). "Notably, proteins such as DKK‐1, VEGF, IL‐8, PDGF‐AA, and angiogenin were downregulated within both the PDAC and TNBC cancer cells." (PMID 40116596, 2025). "Our results revealed that angiogenin down-regulated the secretion of IL-6, IL-8 and MCP-1 pro-inflammatory molecules by cancer cells, suggesting angiogenin could inhibit the inflammation." (PMID 38025776, 2023). "In A172 cancer cells, the mitogen activated protein kinase (MAPK)/extracellular-signal-regulated kinase (ERK) signalling pathway could be responsible of the ANG phosphorylation which prevent the binding with the RI." (PMID 31500197, 2019). "Hypoxia-induced secreted exosomes released from cancer cells contain plasma membrane receptors, including glucose transporter, EGFR, P-glycoprotein, and multidrug resistance protein 1; angiogenic proteins, such as VEGF, FGF, and angiogenin; and various noncoding RNAs, including miRNAs and lncRNAs." (PMID 33946823, 2021). "Despite the complexity of ANG/TIE signaling regulation, the prominent role of ANG2 and the TIE receptors in the regulation of angiogenesis and vascular destabilization shines a light on the potential of ANG2/TIE signaling as a therapeutic target in cancer treatment." (PMID 33217955, 2020). "Results on cell viability/proliferation, cytoskeleton actin, angiogenin translocation and vascular endothelial growth factor (VEGF) release pointed to the promising potentialities of the developed systems as anti-angiogenic tunable nanoplaftforms in cancer cells treatment." (PMID 31500197, 2019). "Further analysis suggested that serum ANG levels may have the potential of being a marker for cancers and cardiovascular diseases but not for other diseases." (PMID 29736193, 2018). "An increase in the levels of ANG and ANGST was observed with an increase in the invasiveness and malignancy of cancer (MIBC and HG), but it was not statistically significant." (PMID 33343662, 2020).
cancer (continued). "The results demonstrate that the storage of the urine samples at room temperature for >120 min significantly increased the levels of MMP9, APOE, ANG, and MMP10, which could change the final results (positive or negative to cancer)." (PMID 39857022, 2025). "Among them, Angiogenin, Osteopontin and Serpin E1 were also highly secreted in HCT-116 and HT-29 cells, which means they could not take the unique role in the further enhancement of cancer malignancy by SCs." (PMID 36465391, 2022).
cardiovascular diseases (29 papers, 2010 to 2025). "Among the circulating cytokines, angiogenin is a potent inducer of neovascularization 11, which has been found to be associated with cardiovascular diseases such as chronic HF, coronary heart disease and cardiogenic shock 12–17, indicating that it may be a novel disease-specific biomarker." (PMID 25124701, 2014). "In our study, the higher levels of TNF-α, IL-1β, and IL-6 in PBMCs from AP individuals were also accompanied by the upregulation of several cardiovascular disease biomarkers like adiponectin and angiogenin." (PMID 35300329, 2022). "This up-regulation of angiogenin in the acute phase of cardiovascular diseases has also been observed in our study by identifying angiogenin in neurons or vessels of the brain within the first 4 days in infarcted areas." (PMID 30008694, 2018). "Here, we performed a meta-analysis of 8 studies investigating the relationships between ANG levels and cardiovascular diseases." (PMID 29736193, 2018). "Regarding ANG levels in specific subtypes of cardiovascular disease, pooled analysis showed that serum ANG levels were elevated in patients with CAD compared with those in healthy controls; however, without significant difference (pooled SMD = 0.435, 95% CI = −0.079 to 0.949, p = 0.097)." (PMID 29736193, 2018). "Angiogenin (ANG) has been shown to be elevated in several cardiovascular diseases." (PMID 27872509, 2016). "Angiogenin (ANG), a multifunctional protein known to induce blood vessel formation, is a potential biomarker for cardiovascular diseases; however, whether it is affected by vitamin D supplementation is not known." (PMID 35205153, 2022). "Angiogenin increases after MI, but is not elevated in patients suffering from stable cardiovascular disease." (PMID 31428150, 2019).
infection (23 papers, 2010 to 2025). The state of being infected such as from the introduction of a foreign agent such as serum, vaccine, antigenic substance or organism. "Two studies showed that 5′-tRFs produced from tRNAGlu in response to Angiogenin signaling after infection by the respiratory syncytial virus directly promote infection." (PMID 32890397, 2020). "The region on SSC 7 (74 Mb) harbors the T-cell receptor alpha locus (TCRA), interferon-stimulated transcription factor 3 gamma (IRF9), and ribonuclease RNase A family 4 (ANG) genes, which have previously been associated with APP natural infection." (PMID 33193739, 2020). "At days 1, 3, and 5 post infection (p.i.), liver, lung and brain were collected for immunofluorescence (IF) studies of R. conorii and angiogenin (ANG)." (PMID 23800282, 2013). "Finally, as an inflammation-induced protein, ANG showed a broad spectrum of antibacterial activity against bacteria and fungi, demonstrating the immunoregulatory role during infection-related immune response." (PMID 37928479, 2023). "All these observations raise an intriguing hypothesis about a novel cytoplasmic role of ANG, which is induced upon infection with Rickettsia and generates tRFs that may play roles in SFG rickettsioses." (PMID 23800282, 2013). "Finally, the restoration of damaged tissues during the initial immune response by angiogenesis, for example, was induced as early as 4 days post infection as documented by an increased expression of angiogenin, annexin a2, fibronectin and ferritin heavy chain." (PMID 23094107, 2012). "Relevant for infection and inflammation, we observed upregulation of DAXX, involved in transcription repression and apoptosis, and ANG, involved in angiogenesis." (PMID 41416938, 2025). "However, murine angiogenin 1 and 4 (Ang1 and Ang4), as well as human angiogenin, have been shown to have microbicidal activity against systemic bacterial and fungal pathogens, suggesting them to function as mediators during innate immune response after infection." (PMID 40586877, 2025). "In the case of infection-induced tRNA halves, our analyses revealed that TLR-activated NF-κB up-regulates the expression levels of ANG mRNA, potentially leading to enhanced levels of ANG protein available for tRNA cleavage." (PMID 33332353, 2020).
neurodegenerative disease (17 papers, 2014 to 2025). A disorder of the central nervous system characterized by gradual and progressive loss of neural tissue and neurologic function. "Genetic studies have shown that certain ANG mutations are related to neurodegenerative diseases, such as ALS and PD." (PMID 29736193, 2018). "Having established optimal differentiation conditions to generate to mature neurons for both SH-SY5Y and VSC4.1 cell lines we studied the expression and distribution of a neurodegenerative disease associated protein angiogenin." (PMID 27391595, 2016). "Despite expressing many positive functions, ANG can favour the growth of solid tumors by inducing neovascularization around the malignant tissue mass, while some ANG mutants are implicated in neurodegenerative diseases, because their dysfunction often leads to motor neurons hypoxia and death." (PMID 34576228, 2021). "Redundancy might be lower in serum-free environments as the nervous system, where several mutations in ANG have been functionally linked to neurodegenerative diseases." (PMID 32785615, 2020). "However, it remains unclear whether serum ANG levels are associated with neurodegenerative diseases." (PMID 29736193, 2018). "The average serum ANG level in patients with neurodegenerative diseases was approximately 368.80 ± 141.42 ng/ml (n = 1026)." (PMID 29736193, 2018). "Based on these results, we reasoned that ANG functional and structural integrity is more important than serum ANG levels with respect to the pathogenesis of neurodegenerative diseases." (PMID 29736193, 2018). "The release of tiRNAs is mediated by angiogenin (ANG), a member of the Vertebrate RNase Superfamily, widely expressed in most tissues and associated to angiogenesis, hematopoiesis, oncogenesis, neurodegenerative diseases, inflammation, and immunity." (PMID 38317956, 2024). "A conclusion could be drawn that PGRN and ANG have common regulatory functions in the progression of neurodegenerative diseases, and tsRNAs are promising candidates that deserve further evaluation as non‐invasive clinical biomarkers." (PMID 33507586, 2021). "Downregulation of ANG, VEGFA, SURF4, and NIPA1 suggests impacts on neurodegenerative diseases and metabolic disorders." (PMID 38681774, 2023). "Regarding ANG levels in specific types of neurodegenerative diseases, serum ANG levels were not significantly different between healthy controls and patients with AD (p = 0.685, n = 225), ALS (p = 0.484, n = 638), and PD (p = 0.72, n = 163)." (PMID 29736193, 2018). "We found that 5 studies were eligible for inclusion in the analysis (SupplementaryTable 1) and that serum ANG levels were not significantly different between patients with neurodegenerative diseases and healthy controls (pooled SMD = 0.012, 95% CI = − 0.379 to 0.403, p = 0.953)." (PMID 29736193, 2018).
kidney diseases (16 papers, 2012 to 2023). "Angiogenin promotes neovascularization and delays the progression of kidney diseases." (PMID 35646873, 2022). "We can suggest that the maintenance of ANG (1‐7) levels after aldosterone stimulation could be clinically relevant, indicating that the development of compounds that promote ANG II cleavage to increase ANG (1‐7) levels, yet await clinical trials to be applied to patients with renal disease." (PMID 31165585, 2019).